RN7SL234P (RNA, 7SL, cytoplasmic 234, pseudogene)
Gene: Miscellaneous RNA gene on chromosome 6 (149,291,352 to 149,291,646, forward strand). Ensembl gene ENSG00000241391.
Homologues: Orthologues: chimpanzee Metazoa_SRP (98% identical), macaque Metazoa_SRP (94% identical). Paralogues in human: RN7SL156P (78% identical), RN7SL33P (78% identical), RN7SL268P (76% identical), RN7SL2 (73% identical), RN7SL775P (72% identical), RN7SL1 (72% identical), RN7SL5P (72% identical), RN7SL526P (71% identical), RN7SL3 (71% identical), RN7SL4P (70% identical), Metazoa_SRP (69% identical), RN7SL317P (69% identical), and 702 more.